SNORD41 (small nucleolar RNA, C/D box 41)
Synonyms: U41; RNU41
Gene: Small nucleolar RNA gene on chromosome 19 (12,706,449 to 12,706,518, reverse strand). Ensembl gene ENSG00000209702.
Gene Ontology:
Biological process: RNA processing
Cellular component: nucleolus
Homologues: Orthologues: chimpanzee SNORD41 (100% identical), macaque SNORD41 (94% identical), mouse Gm25506 (79% identical), rat Snord41 (77% identical).
Diseases named in the same sentence as SNORD41 in open-access papers:
SNORD41 is named in the same sentence as 4 diseases in open-access papers, as found by Europe PMC text mining. Sharing a sentence is not in itself a finding about the gene and the disease. The quoted sentences say what the papers report.
tumor (1 paper, 2021). "For example, we observed that the HOOK2 gene in case 19 was highly expressed in the tumor sample (19T), but not in its matched normal (19N) and stroma (19S) samples, while those genes around HOOK2 (SNORD41, TRIR, and JUNB) had similar levels of expression in all three samples." (PMID 33916417, 2021).
SNORD41 also shares sentences with these, for which no sentence is quoted: cancer (1 paper); infection (1); lung disease (1).